GLI1 (GLI family zinc finger 1)
Diseases named in the same sentence as GLI1 in open-access papers (continued):
Sharing a sentence is not in itself a finding about the gene and the disease.
hepatocellular carcinoma (50 papers, 2012 to 2025). A malignant tumor that arises from hepatocytes. "Increased levels of signaling pathway components (SMO, SHH, Gli1, Gli2) have been observed in hepatocellular carcinoma cells in culture and in cells from tumors excised from patients." (PMID 38927059, 2024). "BMC Cancer 14: 938, 2014; and Gai X, Tu K, Li C, Roberts LR and Zheng X: Histone acetyltransferase PCAF accelerates apoptosis by repressing a GLI1/BCL2/BAX axis in hepatocellular carcinoma." (PMID 37449518, 2023). "Linc01093 triggered the mRNA decay of GLI1 through interaction with IGF2BP1 to suppress hepatocellular carcinoma (HCC progression." (PMID 36221055, 2022). "Hepatic stellate cells are reported to promote angiogenesis in hepatocellular carcinoma via increasing Gli-1 expression that induces the formation of ROS and increases the invasiveness of hepatocellular carcinoma cells." (PMID 35566016, 2022). "One promising substrate of Kat2b in this process is Gli1, which has been identified as a Kat2b binding and acetylation target in hepatocellular carcinoma cells." (PMID 30424580, 2018). "It has also been reported that GLI1 is over-expressed in more than 50% of hepatocellular carcinomas, and inhibition of HH signaling attenuated tumor growth and induced apoptosis." (PMID 26633513, 2015). "In the present study, it was identified that PKM2 and Gli1 expression levels were significantly elevated in hepatocellular carcinoma (HCC) compared with para-carcinoma." (PMID 25289083, 2014). "Pcaf inhibits hepatocellular carcinoma metastasis by targeting GLI-1 to suppress EMT." (PMID 38498906, 2024). "It has been observed that elevated Gli-1 levels serve as a marker for hepatocellular carcinoma." (PMID 37534085, 2023). "IGF2BP1 interacts with and stabilizes GLI1 mRNA from decay in hepatocellular carcinoma." (PMID 37149646, 2023). "Additionally*** ***, KAT2B is also capable of acetylating histone H4, inhibiting AKT signal as well as regulating GLI1/Bcl-2/Bax axis to induce apoptosis, thereby inhibiting occurrence and hepatocellular carcinoma development." (PMID 34130593, 2021). "Activation of GLI target genes, such as ABCC1 and TAP1, is responsible for drug resistance in hepatoma cells, with a CD133−/EpCAM− surface molecular profile, and GLI1 and truncated GLI1 account for the metastatic feature of the hepatoma cells, with upregulation of matrix metalloproteinases." (PMID 33440657, 2021). "Finally, a recent study showed that the short isoform of PHD finger protein 19 (PHF19) interacts with β-TRCP to inhibit Gli1 ubiquitination and thus promoting Hh signaling in hepatocellular carcinoma (HCC)." (PMID 34948134, 2021). "Besides, BCRP was reported to mediate drug resistance in hepatoma cells under the transcriptional control of Gli1/2, and the inhibition of Gli1 or ABCB2 gene expression ameliorated resistance to various chemotherapies in hepatoma cells." (PMID 34322664, 2021). "Suppressing GLI1 or TAP1 gene expression ameliorates drug resistance in hepatoma cells." (PMID 32108992, 2020). "In hepatocellular cancer, Gli1 over-expression is correlated with capsular invasion, advanced tumor stage, vascular invasion and intrahepatic metastasis and interfering with Gli transcription suppresses cell migration by down-regulating matrix metalloprotease (MMP)-2 and MMP-9." (PMID 27533453, 2016). "Importantly, of all the HH signaling molecules analyzed in hepatocellular carcinoma, only GLI1 expression correlated with the poor prognosis in these patients." (PMID 26633513, 2015). "In this context, a previous study shows that KAT2B plays a tumor suppressive role in hepatocellular carcinoma (HCC) via regulating GLI1/BCL2 signaling pathway." (PMID 38641672, 2024). "Overexpression of SASH1 in hepatocellular carcinoma cells was found to inhibit SHH, SMO, PTC, and GLI1 expression, thereby reducing proliferation, migration/invasion, and EMT progression." (PMID 38498906, 2024).
hepatocellular carcinoma (continued). "There was KLF2 down regulation in hepatocellular cancer (HCC) tissue that suppressed the cell growth and metastasis by repressing the Hedgehog/Gli1 signaling cascade." (PMID 37807067, 2023). "Suppression of GLI1/2 by RNA interference approaches or GANT61, a GLI inhibitor, resulted in a decrease in expression of ABCC1 or ABCB2, and partially restored the chemosensitivity in these poorly differentiated hepatoma cells." (PMID 33440657, 2021). "Hypoxia-inducible transcription factor-1 (HIF-1) promoted GLI1 activation and led to an onset of EMT and invasiveness of the hepatoma cells." (PMID 33440657, 2021). "Both GLI1/2 and TAP1 protein levels were significantly elevated in poorly differentiated hepatoma cells." (PMID 32108992, 2020). "Consistent with their mRNA levels, GLI1 and GLI2 protein levels were significantly increased in these four poorly differentiated hepatoma cell types." (PMID 32108992, 2020). "Consistently, silencing of CK2α inhibits migration and invasion and reduces the expression of GLI1 and PTCH1 in hepatocellular carcinoma Hep G2 cells." (PMID 30934935, 2019). "PCAF can induce cell apoptosis by modulating the GLI1/BCL-2/BAX axis or by acetylating histone H4 and inactivating AKT signaling, which in turn suppresses hepatocellular carcinoma progression." (PMID 30833716, 2019). "In hepatocellular carcinoma (HCC), inhibition of Rab23, a protein belonging to the Rab family of GTPases, negatively regulates the Shh signalling pathway and decreases the expression, nuclear translocation and localisation of Gli1 via GDP/GTP binding." (PMID 29899399, 2018). "In hepatocellular carcinoma patients, increased levels of PTCH1 and GLI1 mRNAs showed significant correlation with recurrence of the disease after surgical resection." (PMID 26633513, 2015). "Another study showed that silencing CK2α inhibited the expressions of Gli1 and Patched homolog 1 (PTCH1) in hepatocellular carcinoma, resulting in the inactivation of Hh signaling pathway." (PMID 25422081, 2014). "Moreover, PHF14 and PHF19 are identified as key players in glioblastoma, colorectal, and hepatocellular cancers, influencing crucial pathways such as Wnt, AKT, ERK1/2, and Hedgehog-Gli1." (PMID 38813086, 2024). "In addition, GLI1 editing promotes a metabolic shift to oxidative phosphorylation to sustain stemness through PINK1/Parkin-mediated mitophagy in hepatocellular carcinoma (HCC), therefore enhancing metastatic potential and sorafenib resistance of HCC." (PMID 39035027, 2024). "We have demonstrated that Hh transcription factors GLI1/2 were able to bind to the consensus sequence in the promoter of ABCC1 or ABCB2 to facilitate resistance to sorafenib, doxorubicin and cisplatin in poorly differentiated hepatoma cells." (PMID 33440657, 2021). "It has also been reported that Hh signaling was active in hepatocellular carcinoma (HCC) cells, inhibition of Hh signaling by GLI1/2 inhibitor GANT61-induced autophagy, while activation of Hh signaling by Hh ligand protein or Hh agonist prevented the autophagy induction." (PMID 30081498, 2018). "Cai and colleagues reported that PKCα increases Gli1 activity via MEK/ERK pathway and PKCδ negatively regulates Gli1 expression through transcriptional down-regulation of GLI1 mRNA in NIH/3T3 cells and human Hepatoma Hep3B Cells." (PMID 26343727, 2015). "In hepatocellular carcinoma (HCC) progression, PHF19 influences the Hedgehog-Gli1 signaling pathway." (PMID 38813086, 2024). "However, in human hepatoma Hep3B cells PKCδ has been shown to repress GLI1 transcriptional activity and nuclear localization, without affecting protein stability." (PMID 30934935, 2019). "Sema3C has recently been studied as a novel biomarker in Hepatocellular carcinoma (HCC), where NRP1 and Integrin Beta1 (ITGβ1) act as functional receptors of Sema3C which activates Serine threonine Kinase (AKT)/GLI Family Zinc Finger 1 (Gli1)/c-Myc signaling pathways leading to tumor initiation." (PMID 40277760, 2025).
hepatocellular carcinoma (continued). "GANT61, a selective inhibitor of GLI1 and GLI2, was reported as a promising treatment for cancer in various tissues; however, the biological impact of GANT61 in hepatocellular carcinoma (HCC), especially in undifferentiated HCC cells, remains unclear." (PMID 32354204, 2020). "Xu and colleagues described for the first time the negative role of AMPK in the regulation of HH pathway in hepatocellular carcinoma, where AMPK directly interacts with GLI1 and modulates its expression." (PMID 30934935, 2019).
ovarian carcinoma (46 papers, 2009 to 2025). A malignant neoplasm originating from the surface ovarian epithelium. "GLI1 was clinically associated with chemotherapy treatments and the survival of ovarian cancer patients." (PMID 32242101, 2020). "Then, Smo transduces the signal by activating Gli‐1.22, 23 Aberrant activation of the Shh pathway is closely associated with tumorigenesis and progression of ovarian cancer." (PMID 30338663, 2018). "Inhibition of GLI1 in ovarian cancer cells that are resistant to cisplatin caused an accumulation of cisplatin in the nucleus." (PMID 26633513, 2015). "Other analyses of ovarian carcinoma samples have suggested that elevated Gli1 protein expression is an independent factor associated with decreased survival when adjusting for age, stage, grade and histologic type." (PMID 22140510, 2011). "However, previous studies reported that GLI1 overexpression in malignant ovarian epithelial tumor enables tumor metastasis and increase risk in ovarian cancer patient." (PMID 31973134, 2020). "Gli1 also is implicated in chemoresistance in ovarian cancer cells." (PMID 30042330, 2018). "Aberrant expression of the Hedgehog signaling pathway transcription factor Gli1 has been found to be involved in the modulation of ABCB1 in ovarian cancer." (PMID 38228910, 2024). "Similar results were observed in ciliated SKOV3 ovarian cancer cells that enrich SMO in response to SAG stimulation but fail to activate GLI1." (PMID 37830570, 2023). "GANT-61 inhibits both Gli1/2 downstream effectors and decreases tumor growth in vivo and in vitro in a variety of cancers, including prostate and ovarian cancers." (PMID 37305676, 2023). "The molecular mechanism of miR-324-5p in targeting GLI1 in ovarian cancer cells is probably through Hedgehog pathway." (PMID 32986358, 2020). "The expression of the chemotherapy-induced upregulated EMT markers (VIM and Snail) and stem cell markers (CD44 and CD133) in ovarian cancer was also reserved by GLI1 knockdown." (PMID 32242101, 2020). "Survival analysis was performed using the PROGgeneV2 database, to explore the relationship between the expression of GLI1 and overall survival of ovarian cancer samples." (PMID 32242101, 2020). "The expression of GLI1 in clinical samples from ovarian cancer patients who went through chemotherapy (chemotherapy group) or not (non-chemotherapy group) was also analysed." (PMID 32242101, 2020). "Our studies further reveal the putative upstream involvement of PDGF-BB/PDGFR-β potentiating CSC/MSC Hedgehog signaling through PTCH, SMO and GLI1, all documented to result in platinum resistance of ovarian cancer." (PMID 32726910, 2020). "Gant61 treatment in ovarian cancer cells showed a reduction in migration with downregulation of GLI1 activity." (PMID 33396427, 2020). "Gli1 is elevated in several ovarian cancer cell lines (OVCAR5, OV-202, and OV-167) compared with normal ovarian surface epithelium." (PMID 30042330, 2018). "We found that Shh, Ptch1, Smo, and Gli‐1 were overexpressed at the protein level in all ovarian cancer cells compared with HOSEPICs." (PMID 30338663, 2018). "Our study revealed elevated protein expression of Shh, Ptch1, Smo, and Gli‐1 in four ovarian cancer cells compared to HOSEPICs, indicating that Hh signaling is activated in ovarian cancer." (PMID 30338663, 2018). "Current findings suggest that Gli1 has an important role in ovarian cancer stemness, tumorigenicity, and chemoresistance." (PMID 30042330, 2018). "Both cell culture and patient studies suggest an important role for Gli1 and Hh signaling in ovarian cancer chemoresistance." (PMID 30042330, 2018). "Addressing this issue therapeutically, we show that a pharmacological approach combining a DYRK1B antagonist with an mTOR/AKT inhibitor results in strong GLI1 targeting and in pronounced cytotoxicity in human pancreatic and ovarian cancer cells." (PMID 27903983, 2017).
ovarian carcinoma (continued). "Selective inhibition or knockdown of SMO and other Hedgehog downstream effectors (e.g. Gli1) increased cDDP sensitivity in ovarian cancer cell cultures and xenografts." (PMID 26910918, 2017). "These two effects correlate with increased and decreased expression of Gli1, which is amplified in ovarian cancer stem-like cells respectively." (PMID 28134850, 2017). "Meanwhile, GLI1 contributed to cellular resistance through altering cellular drug accumulation in the ovarian cancer." (PMID 28446712, 2017). "Ovarian cancer cells overexpressing GLI1 showed increased proliferation, mobility, invasiveness and up-regulation of E-cadherin and vimentin." (PMID 26633513, 2015). "In human ovarian cancer cells knocking down GLI1 inhibited the up-regulation of the BER essential XRCC1 gene." (PMID 26197339, 2015). "Downregulation of GLI1 in cisplatin-treated ovarian cancer cells blocked the expression of c-JUN along with excision repair cross-complementing 1 (ERCC1), XRCC1 and xeroderma pigmentosum group D (XPD)." (PMID 26633513, 2015). "In this study, we employed GANT61, a small molecule inhibitor of both Gli1 and Gli2, to identify unique downstream targets of the GLI genes that function specifically in cellular migration and invasion in ovarian cancer." (PMID 24533083, 2014). "To investigate a putative role for Gli1 in ovarian cancer, we first determined protein level in three human ovarian carcinoma cell lines A2780, SKOV-3 and OVCAR-3." (PMID 23555905, 2013). "Results obtained showed that epithelial cells in ovarian cancer tissue express significantly higher levels of nuclear Gli1 than in normal ovarian tissue, where the protein was almost undetectable." (PMID 23555905, 2013). "To confirm that the reduction of cell proliferation in vitro by KAAD-cyclopamine was due to specific inhibition of the Hh pathway, we analyzed the change in mRNA and protein Gli1 levels in drug-treated ovarian carcinoma cell lines." (PMID 23555905, 2013). "To this end we firstly assessed by immunocytochemical and immunoblot analysis the expression of Gli1 in different ovarian cancer cell lines, i.e. A2780, SKOV-3 and OVCAR-3, these studies revealing similar protein expression in all 3 cell lines examined." (PMID 23555905, 2013). "In vitro experiments demonstrated Gli1 expression in the three ovarian carcinoma cell lines tested, A2780, SKOV-3 and OVCAR-3." (PMID 23555905, 2013). "Blocking the Hh signal using either cyclopamine or Gli1 siRNA resulted in remarkably decreased cell proliferation in ovarian carcinoma cells." (PMID 23303278, 2013). "Next, we examined the expression of Gli1 in ovarian cancer cell lines, and the in vitro effects of a specific hedghehog pathway blocker, KAAD-cyclopamine or a specific Gli1 inhibitor, GANT58, on cell proliferation and on hedgehog target gene expression." (PMID 23555905, 2013). "Previous studies have reported elevated Gli1 expression in ovarian cancer cell lines and primary human ovarian tumor samples." (PMID 22140510, 2011). "Altered gene and protein expression of the Hh pathway members Gli1, Smo, Ptch1, Desert hedgehog (Dhh) and Sonic hedgehog (Shh) in ovarian cancer has been reported, although the exact prevalence and pattern remains to be clarified." (PMID 22140510, 2011). "Notably, however, PTCH1 and GLI1 exhibited elevated expression levels in the primary ovarian cancer cell lines TOV112D and COV434." (PMID 40565349, 2025). "Upon treatment with cisplatin, ovarian cancer cell lines upregulated proteins associated with nucleotide excision repair, including ERCC1, XPD helicase, and XRCC1, a response which was blocked by shRNA knockdown of Gli1." (PMID 37954979, 2023). "Even between ovarian cancer cell lines, evidence exists for both Gli1 and Gli2-driven mechanisms, and it is unclear whether one or both are required for expression of ABCB1." (PMID 37954979, 2023).